KPNA7 (karyopherin subunit alpha 7)
Description:
Functions in nuclear protein import.
Synonyms: IPOA8; OZEMA17
Tractability: No criterion of Open Targets' tractability assessment is met for any kind of drug.
Gene: Protein-coding gene on chromosome 7 (99,173,572 to 99,250,075, reverse strand). Ensembl gene ENSG00000185467.
Subcellular location: Nucleus
Pathways (Reactome):
Disease: Maturation of DENV proteins; NS1 Mediated Effects on Host Pathways
Immune System: ISG15 antiviral mechanism
Gene Ontology:
Molecular function: protein binding; nuclear import signal receptor activity
Biological process: protein import into nucleus
Cellular component: NLS-dependent protein nuclear import complex; nucleus; cytosol; nucleoplasm; cytoplasm; spindle
Genetic constraint (gnomAD): Loss-of-function variants: 50 observed, 50.85 expected, observed/expected ratio (o/e) 0.98, 90% interval 0.78 to 1.25. The upper end of that interval is the gene's LOEUF score, 1.25, which puts it in group 5 of 6, group 1 being the genes least tolerant of losing a copy. Missense variants: 595 observed, 614.18 expected, observed/expected ratio (o/e) 0.97, 90% interval 0.9 to 1.04. Synonymous variants: 258 observed, 254.26 expected, observed/expected ratio (o/e) 1.01, 90% interval 0.92 to 1.12.
Gene-disease validity (ClinGen):
ClinGen rates the evidence that KPNA7 causes each of these diseases.
epilepsy (autosomal recessive): Limited. A brain disorder characterized by episodes of abnormally increased neuronal discharge resulting in transient episodes of sensory or motor neurological dysfunction, or psychic dysfunction.
Homologues: Orthologues: chimpanzee KPNA7 (99% identical), macaque KPNA7 (95% identical), dog KPNA7 (81% identical), rabbit KPNA7 (79% identical), pig KPNA7 (75% identical), guinea pig KPNA7 (69% identical), rat Kpna7 (63% identical), mouse Kpna7 (60% identical), tropical clawed frog kpna7 (59% identical), zebrafish kpna7 (52% identical), Caenorhabditis elegans F53B2.5 (21% identical), Caenorhabditis elegans ima-1 (20% identical). Paralogues in human: KPNA2 (54% identical), KPNA4 (43% identical), KPNA3 (42% identical), KPNA1 (41% identical), KPNA6 (41% identical), KPNA5 (41% identical).
Diseases named in the same sentence as KPNA7 in open-access papers:
KPNA7 is named in the same sentence as 13 diseases in open-access papers, as found by Europe PMC text mining. Sharing a sentence is not in itself a finding about the gene and the disease. The quoted sentences say what the papers report.
pancreatic cancer (8 papers, 2017 to 2023). "KPNA7 depletion results in extensive nuclear lobulation and loss of circularity in pancreatic cancer cells." (PMID 34685604, 2021). "Initial reports identified overexpressed KPNA7 in multiple pancreatic cancer cell lines that implicated overactive transport of KPNA7 cargoes." (PMID 31867128, 2018). "In addition, recent computational analysis implicated KPNA7 as a potential biomarker for pancreatic cancer." (PMID 29580221, 2018). "Depletion of KPNA7 in pancreatic cancer cells led to reduced proliferation rates and defects in mitosis." (PMID 34685604, 2021). "The KPNA7 gene occurs within the 7q21-q22 amplicon, a region frequently amplified in pancreatic cancer." (PMID 34685604, 2021). "In an earlier study, we showed that KPNA7 is an important regulator of pancreatic cancer cell growth in cell lines harboring amplification and high-level overexpression of the gene." (PMID 29580221, 2018). "We previously showed that amplification and subsequent overexpression of KPNA7 leads to promotion of cell growth in Hs700T and AsPC-1 pancreatic cancer cell lines." (PMID 29580221, 2018). "In our previous work we pinpointed KPNA7 as a regulator of malignant properties in pancreatic cancer cells with high KPNA7 expression." (PMID 29580221, 2018). "detailed the involvement of a nuclear transport protein, KPNA7, with promotion of malignancy in pancreatic cancer." (PMID 28918032, 2017). "Although a few potential cargos of KPNA7 have been identified in pancreatic cancer cell lines and KPNA7-overexpressing HEK293 T lines, up until now, there has, to our knowledge, been no report on specific candidate substrates that function in human oocytes and early embryos." (PMID 36647821, 2023). "KPNA7 was reported to promote malignant properties of pancreatic cancer cells in vitro, while the exact function of KPNA2 in PDAC remains unclear." (PMID 33728352, 2021). "In addition, the growth inhibition phenotype was detected both in pancreatic and breast cancer cell lines, indicating that the role of KPNA7 is not limited to pancreatic cancer." (PMID 29580221, 2018). "KPNA7 is mainly expressed during early embryogenesis and in oocytes in different animals and has been identified as one of the target genes for the 7q21-22 amplicon in pancreatic cancer." (PMID 29580221, 2018). "In vitro experiments had demonstrated that KPNA7 was up-regulated in pancreatic cancer." (PMID 28611293, 2017). "KPNA7 is not expressed in most adult tissues but is expressed in some human pancreatic cancers and pancreatic cancer cells." (PMID 34685604, 2021).
breast carcinoma (2 papers, 2015 to 2018). "KPNA7 depletion also induced distinct changes in the nuclear morphology in both Hs700T pancreatic and T-47D breast cancer cells." (PMID 29580221, 2018). "Here we extend these findings to show that even low KPNA7 expression plays an important role in the proliferation of both pancreatic and breast cancer cells." (PMID 29580221, 2018). "The results showed that KPNA1 to 6 was highly expressed in all 11 breast cancer cell lines as well as in normal mammary gland tissue, while focal KPNA7 expression was observed in the SK-BR-3 and HCC1143 cell lines." (PMID 26052702, 2015). "Likewise, the other pancreatic and breast cancer cell lines exhibited statistically significant decreases in proliferation after KPNA7 knock-down." (PMID 29580221, 2018). "In this study, we demonstrate that the silencing of KPNA7, the least studied member of the karyopherin alpha family of nuclear transport proteins, leads to a distinct inhibition of pancreatic and breast cancer cell proliferation, in spite of the endogenous expression level." (PMID 29580221, 2018). "In the present study, we show that the silencing of KPNA7 results in a dramatic reduction in pancreatic and breast cancer cell growth, irrespective of the endogenous KPNA7 expression level." (PMID 29580221, 2018).
female infertility (2 papers, 2023). Diminished or absent ability of a female to achieve conception. "By using the strategy, LHX8 and KPNA7 variants were identified to cause female infertility." (PMID 37052235, 2023). "Here, we confirmed the role of KPNA7 in human early embryonic development, and this finding expands human karyopherin-related disorders to include PREMBA and female infertility and establishes human disease caused by abnormality in karyopherin α." (PMID 36647821, 2023).
COVID-19 (1 paper, 2021). A disease caused by infection with severe acute respiratory syndrome coronavirus 2. "Results showed that COVID-19 patients had higher KPNA5 and lower KPNA7 expression compared with non-COVID-19 patients (p = 0.0025 and, p = 0.0017, respectively)." (PMID 34696514, 2021). "COVID-19 patients showed alterations in KPNA3, KPNA5, KPNA7, KPNB1, RHOA, and CDC42 expression compared with non-COVID-19 patients." (PMID 34696514, 2021).
epilepsy (1 paper, 2020). "The CTCF binding motif in exon 7 (c.1020-1038) of KPNA7 overlaps the epilepsy-associated c.1030G > C transversion." (PMID 32179771, 2020). "Exome sequencing of siblings with severe neurodevelopmental defects and clinical features of epilepsy identified two amino acid-altering mutations in KPNA7." (PMID 32179771, 2020). "We next tested how the epilepsy-associated mutations in KPNA7 affect binding to the hnRNP R NLS." (PMID 32179771, 2020). "Our data support a role for altered neuronal expression and activity of KPNA7 in a rare type of pediatric epilepsy." (PMID 32179771, 2020).
Meier-Gorlin syndrome (1 paper, 2024). "Among the interactions, we uncover a novel nuclear localisation signal (NLS) in the Cell division control protein 45 (CDC45) that binds importin subunit α-8 (KPNA7), and is disrupted by a R157C mutation associated with a developmental disorder called Meier-Gorlin syndrome." (PMID 39009827, 2024). "This is highlighted by the newly discovered interaction between CDC45 and KPNA7, for which we demonstrated that the R157C CDC45 mutation, associated with Meier-Gorlin syndrome, disrupts KPNA7 binding and results in the delocalisation of CDC45 from the nucleus." (PMID 39009827, 2024).
otosclerosis (1 paper, 2026). Formation of spongy bone in the labyrinth capsule which can progress toward the stapes (stapedial fixation) or anteriorly toward the cochlea leading to conductive, sensorineural, or mixed hearing loss. "This study expands the phenotypic spectrum of KPNA7 and provides new insights into the pathobiology of otosclerosis." (PMID 42278511, 2026).
cancer (2 papers, 2018 to 2019). A tumor composed of atypical neoplastic, often pleomorphic cells that invade other tissues. "The targeting of KPNA7 would avoid this problem as its expression is in the current light mainly limited to cancer." (PMID 29580221, 2018). "The growth-promoting role and the expression pattern of KPNA7 makes it an interesting target for the development of cancer therapies." (PMID 29580221, 2018). "We used siRNA-based knock-down of KPNA7 in cancer cell lines, followed by functional assays (proliferation and cell cycle) and immunofluorescent stainings to determine the role of KPNA7 in regulation of cancer cell growth, proper mitosis and nuclear morphology." (PMID 29580221, 2018). "This led us to question whether low level KPNA7 expression also confers a growth benefit to cancer cells." (PMID 29580221, 2018). "Taken together, our data provide new important evidence on the contribution of KPNA7 to the regulation of cancer cell growth and the maintenance of nuclear envelope environment, and thus deepens our understanding on the impact of nuclear transfer proteins in cancer pathogenesis." (PMID 29580221, 2018). "Moreover, lower levels of KPNA7 expression was detected in cancer cells without amplification whereas no or very low level expression expression was found in normal adult tissues with the exception of ovary and trachea, indicating re-activation of the gene in cancer cells." (PMID 29580221, 2018). "Karyopherin alpha 7 (KPNA7), the newest member of the karyopherin alpha nuclear importer family, is expressed at a high level during embryogenesis, reduced to very low or absent levels in most adult tissues but re-expressed in cancer cells." (PMID 29580221, 2018).
infection (1 paper, 2025). The state of being infected such as from the introduction of a foreign agent such as serum, vaccine, antigenic substance or organism. "In addition, the expression levels of KPNB1, KPNA1, KPNA2, KPNA4, KPNA6, and KPNA7 changed with the infection time of the three strains while KPNA3 and KPNA5 did not change with the incubation time." (PMID 40687856, 2025).
neurodevelopmental disorder (1 paper, 2023). A behavioral and cognitive disorder with onset during the developmental period that involves impaired or aberrant development of intellectual, motor, or social functions. "However, recent evidence indicates that loss of function mutations of KPNA7 in patients affected by neurodevelopmental disorders significantly reduced the ability of KPNA7 to transport cargoes across the nuclear membrane." (PMID 37792911, 2023).
KPNA7 also shares sentences with these, for which no sentence is quoted: cerebellar malformation (1 paper); infantile spasms (1); tumour (1).